RN7SL596P (RNA, 7SL, cytoplasmic 596, pseudogene)
Gene: Miscellaneous RNA gene on chromosome 11 (63,797,784 to 63,798,071, reverse strand). Ensembl gene ENSG00000264519.
Homologues: Orthologues: chimpanzee Metazoa_SRP (96% identical). Paralogues in human: Metazoa_SRP (84% identical), RN7SL774P (82% identical), RN7SL811P (82% identical), RN7SL134P (82% identical), Metazoa_SRP (81% identical), RN7SL96P (81% identical), Metazoa_SRP (80% identical), RN7SL163P (80% identical), RN7SL784P (80% identical), RN7SL510P (79% identical), RN7SL488P (79% identical), RN7SL391P (78% identical), and 705 more.